JAK1 (Janus kinase 1)
Diseases named in the same sentence as JAK1 in open-access papers (continued):
Sharing a sentence is not in itself a finding about the gene and the disease.
haemorrhage (1 paper, 2024). "For example, CUR alleviates neuronal apoptosis and neuroinflammation induced by cerebral haemorrhage by inhibiting the JAK1/STAT1 pathway and inhibits IL-1β-induced chondrocyte apoptosis by activating autophagy and inhibiting the NF-κB pathway." (PMID 39000093, 2024).
HIV-1 infection (1 paper, 2025). The type species of lentivirus and the etiologic agent of acquired immunodeficiency syndrome (AIDS). "Furthermore, individuals with the TG genotype at JAK1 rs4244165 were associated with an increased risk of HIV-1 infection compared to those with the GG genotype (p = 0.019, OR = 1.373, 95% CI 1.054–1.788)." (PMID 40331958, 2025). "The results revealed significant association between five SNPs (NLRP3 rs4612666, MAVS rs17857295, MAVS rs6084497, MAVS rs16989000, and JAK1 rs4244165) and HIV-1 infection." (PMID 40331958, 2025).
Hutchinson-Gilford progeria syndrome (1 paper, 2022). "In addition, JAK inhibitors, such as the JAK1/2 inhibitor ruxolitinib, alleviate premature aging effects for the Hutchinson-Gilford progeria syndrome." (PMID 35154123, 2022).
hyperphosphatemia (1 paper, 2023). Abnormally high level of phosphate in the blood. "Herein, we show that hyperphosphatemia induces the phosphorylation of JAK1 and JAK3 and of the downstream effector STAT1 in HASMCs." (PMID 38254629, 2023).
Hypoglycemia (1 paper, 2025). A decreased concentration of glucose in the blood. "Treatment with the JAK1/2 inhibitor ruxolitinib significantly improved survival by preventing lethal hypoglycemia and suppressing hyperinflammation." (PMID 40702267, 2025). "Moreover, we identify the therapeutic potential of ruxolitinib, a JAK1/2 inhibitor, in treating malaria-induced hypoglycemia and cytokine storm, advocating for its further investigation as a novel treatment for severe malaria." (PMID 40702267, 2025).
Kawasaki disease (1 paper, 2021). A rare inflammatory disease characterized by an acute febrile, systemic, self-limiting, medium-vessel vasculitis primarily affecting children. "We speculate that the RPN2/JAK1/STAT3 axis could be a potential therapeutic target in Kawasaki disease because of its known effect on inflammatory reactions." (PMID 33692975, 2021).
keloid (1 paper, 2021). An irregularly shaped, elevated mark on the skin caused by deposits of excessive amounts of collagen during wound healing. "In healthy volunteer fibroblasts, folic acid exposure recapitulated the exaggerated closure and hyper-glycolytic state of keloid fibroblasts through JAK1/2- and STAT3-dependent pathways." (PMID 33662027, 2021). "Although the JAK1/2 inhibitor ruxolitinib inhibited the hyperactivity of a representative keloid fibroblast cell line in the scratch assay, it worsened the hyper-glycolytic state." (PMID 33662027, 2021). "Moreover, our findings are consistent with other groups identifying that JAK1/2 signaling blockade reverses abnormal phenotypes in keloid-derived cells." (PMID 33662027, 2021). "Our work expands on the current literature to directly link JAK1/2, STAT3, and HIF1α to keloid pathology, folic acid responses, and Warburg physiology; however, other signaling pathways beyond these identified pathways are likely involved for each finding." (PMID 33662027, 2021). "Furthermore, while our findings reproduce the findings of prior reports identifying JAK1/2, STAT3, and folate as targetable pathways for the treatment of keloids, a potentially contrasting role for vitamin D impacting STAT3 signaling and risk of keloids in pigmented skin should also be considered." (PMID 33662027, 2021).
kidney cancer (1 paper, 2026). Primary or metastatic malignant neoplasm involving the kidney. "Together, these findings reveal a targetable enhancer mechanism that sustains HIF-2α expression and suggest that combined inhibition of JAK1/STAT3 and HIF-2α may overcome therapeutic resistance in kidney cancer." (PMID 41874563, 2026).
laryngeal carcinoma (1 paper, 2024). Carcinoma that arises from the laryngeal epithelium. "It was demonstrated that esculetin significantly inhibited the proliferation, migration, and invasion of laryngeal cancer Hep-2 cells and significantly inhibited the phosphorylation of Janus kinase 1 (JAK1), JAK2, and STAT3 in Hep-2 cells." (PMID 39346560, 2024).
leishmaniasis (1 paper, 2023). Infectious disease that is transmitted through the bite of hematophagous female phlebotomine sand flies. "We previously found that blocking NKG2D or blocking Jak1/3 signaling in a mouse model of leishmaniasis ameliorated severe disease." (PMID 37603573, 2023).
Lung disease (1 paper, 2022). "Lung disease is the leading cause of morbidity and mortality in these two disorders which do not respond to conventional immunosuppressive therapies and only partially to JAK1/2 inhibitors." (PMID 35159128, 2022).
lymph node metastasis (1 paper, 2021). "In addition, the higher expression of JAK1 is associated with preferable OS in patients with N2 lymph node metastasis (HR: 0.39, 95% CI from 0.17 to 0.86, P = 0.016) without distant metastasis (HR: 0.73, 95% CI from 0.56 to 0.93, P = 0.013) of NSCLC." (PMID 34587898, 2021).
Lynch syndrome (1 paper, 2023). An autosomal dominant hereditary neoplastic syndrome characterized by the development of colorectal carcinoma and a high risk of developing endometrial carcinoma, gastric carcinoma, ovarian carcinoma, renal pelvis carcinoma, and small intestinal carcinoma. "While various biomarkers of response have been evaluated in the context of MSI CRC, including B2M and JAK1/2 mutations, TMB, WNT pathway mutations, and Lynch syndrome, with mixed results, liver metastases have been associated with a lack of activity in such strategies." (PMID 37686520, 2023).
macular oedema (1 paper, 2021). "Our results suggest that IL-17A can damage the BRB through the activating the JAK1 signaling pathway, and targeting this pathway may be a novel approach to treat inflammation-induced macular oedema." (PMID 34356895, 2021). "Our results suggest that Tofacitinib or other JAK1 inhibitors may be re-purposed for the management of IL-17A mediated macular oedema." (PMID 34356895, 2021). "Since JAK1 is also involved in the signal transduction of other barrier-damaging cytokines, such as IL-6 and VEGF, targeting this pathway may be a novel approach for the management of macular oedema, particularly those who are resistant to anti-VEGF therapy." (PMID 34356895, 2021).
membranous nephropathy (1 paper, 2021). "One previously reported individual developed membranous nephropathy that recurred despite renal transplantation and eventually necessitated hemodialysis, although other patients with gain-of-function variants in JAK1, including the present case, did not develop any renal impairment." (PMID 35046931, 2021).
mood disorder (1 paper, 2025). A cognitive disorder a disturbance in which the person's mood is hypothesized to be the main underlying feature. "The excessive expression of inflammatory factors can activate the JAK1/STAT3 pathway, which may lead to hippocampal neuronal damage, impair learning and memory abilities, and exacerbate mood disorders." (PMID 40076470, 2025).
myxoid liposarcoma (1 paper, 2022). A liposarcoma characterized by the presence of round non-lipogenic primitive mesenchymal cells and small signet ring lipoblasts within a myxoid stoma with a branching vascular pattern. "We validated CD44 as a target gene of JAK1/2 inhibition and as a potential cancer stem cell marker in myxoid liposarcoma." (PMID 35186752, 2022).
neuropathy (1 paper, 2022). A disorder affecting the nervous system that manifests with pain, tingling, numbness, and/or muscle weakness. "Well-tolerated AE were observed, but with a high presence of neuropathy due to nab-paclitaxel and momelotinib (an agent with inhibitory activity of Janus kinase 1 and 2)." (PMID 35330078, 2022).
non-Hodgkin lymphoma (1 paper, 2023). Distinct from Hodgkin lymphoma both morphologically and biologically, non-Hodgkin lymphoma (NHL) is characterized by the absence of Reed-Sternberg cells, can occur at any age, and usually presents as a localized or generalized lymphadenopathy associated with fever and weight loss. "Cerdulatinib, a JAK1/2 inhibitor, is undergoing clinical trials for treatment of non-Hodgkin’s lymphoma [NCT04757259]." (PMID 37305676, 2023).
Oral ulcer (1 paper, 2025). Erosion of the mucous mebrane of the mouth with local excavation of the surface, resulting from the sloughing of inflammatory necrotic tissue. "Following secondary loss of response to Ustekinumab, compassionate treatment with Upadacitinib, a recently developed oral Jak-1 selective inhibitor, resulted in the complete resolution of the oral ulcers." (PMID 40710828, 2025).
osteonecrosis (1 paper, 2024). A none disease characterized by death of bone tissue due to a lack of blood supply. "EP300, TRAF6, STAT1, JAK1, CASP8, and JAK2 have exhibited significant differences in SANFH (spontaneous osteonecrosis of the femoral head)." (PMID 38204239, 2024). "In conclusion, EP300, TRAF6, STAT1, JAK1, CASP8, and JAK2 exhibit significant differences in SANFH (spontaneous osteonecrosis of the femoral head)." (PMID 38204239, 2024).
otitis externa (1 paper, 2024). Inflammation of the anatomical structures of the outer ear and ear canal secondary to an infectious process. "The cat had been treated for chronic dermatitis and otitis externa for over 3 months with oclacitinib, a drug that modulates the activity of Janus kinase 1 and has immunosuppressive properties." (PMID 39212262, 2024).
ovarian endometrioid carcinoma (1 paper, 2025). "These included alterations in RAD51C, NOTCH4, SMARCA4, SMARCA1 and JAK1 in ovarian endometrioid carcinomas and SMARCA4 genes in ovarian mucinous carcinomas." (PMID 40981433, 2025).
ovarian mucinous carcinomas (1 paper, 2025). "In addition to identifying genes previously known to be involved in these tumors, we identified alterations in RAD51C, NOTCH4, SMARCA1/4, and JAK1 in ovarian endometrioid, ESR1 in uterine endometrioid, and SMARCA4 in ovarian mucinous carcinomas." (PMID 40981433, 2025).
papillary thyroid cancer (1 paper, 2024). "Our data indicated that the JAK1/2-STAT3 signaling pathway is significantly upregulated in ATC tumor tissues than in normal thyroid and papillary thyroid cancer tissues." (PMID 38336839, 2024). "This study successfully verified the activation of the JAK1/2-STAT3 signaling pathway within the tumor tissues of ATC patients, which showed a distinct contrast when compared to papillary thyroid cancer (PTC) and normal thyroid (NT) tissues." (PMID 38336839, 2024).
penile cancer (1 paper, 2024). A primary or metastatic malignant neoplasm that affects the penis. "During malignant progression phase of penile cancer, the expression evolution of JAK-STAT-SOCS1 axis was characterized by the upregulation of JAK1, JAK3, STAT4, STAT5A and STAT6." (PMID 38774752, 2024).
pericarditis (1 paper, 2024). An inflammatory process affecting the pericardium. "Eleven variants were located in genes already associated with recurrent pericarditis (NLRP3, TNFRSF1A and MEFV) and five in inflammation/immunodeficiency-related genes (IFIH1, NFKBIA, JAK1, NOD2 and ALPK1)." (PMID 39347728, 2024).
polymyositis (1 paper, 2025). A rare idiopathic inflammatory myopathy characterized by symmetric proximal muscle weakness and elevated muscle enzymes. "The overexpression of IL21 in affected dogs is associated with activating the JAK1 and JAK3 receptors, suggesting that targeting this signalling cascade with JAK inhibitors may provide a novel therapeutic approach for polymyositis in the Dutch Kooiker dog." (PMID 40520426, 2025).
preeclampsia (1 paper, 2023). Preeclampsia is a hypertensive disorder of pregnancy that is characterized by new-onset hypertension with proteinuria presenting after 20 weeks of gestation, and depending on mild or severe forms may initially present with severe headache, visual disturbances, and hyperreflexia. "Additionally, it has been discovered that down-regulation of Annexin7 in placenta of preeclampsia patients inhibits the JAK1/STAT3 pathway in trophoblast cells, leading to a decrease in BCL2 protein levels and induction of cell apoptosis, thus contributing to the development of preeclampsia." (PMID 38235138, 2023).
primary biliary cholangitis (1 paper, 2020). Primary biliary cholangitis (PBC) is a chronic and slowly progressive cholestatic liver disease of autoimmune etiology characterized by injury of the intrahepatic bile ducts that may eventually lead to liver failure. "Our results suggest that hsa-miR-23b is involved in pathophysiology of primary biliary cholangitis through interleukin-12 signaling via regulation of CNN2, JAK1, LMNB1, MTAP, SOD2, and TCP1." (PMID 33036164, 2020).
proteinopathy (1 paper, 2026). "Similar findings were obtained by crossing DRM mice with the cardiomyocyte-specific Jak1 knockout, suggesting JAK1 as a therapeutic target in proteinopathy." (PMID 41917326, 2026).
prurigo nodularis (1 paper, 2026). Prurigonodularis (PN) is a skin disease in which hard crusty lumps are formed on the skin that itches intensely. "Prurigo simplex and prurigo nodularis are chronic, pruritic dermatoses with complex, cytokine-driven immunopathogenesis involving the JAK1-STAT signaling pathway." (PMID 42186623, 2026).
rectal cancer (1 paper, 2025). A primary or metastatic malignant neoplasm that affects the rectum. "The combination of ASCC3 with several immune-related genes, including JAK1, NFKB1, SEMA5A, NR2C2, CNTF and CREB1, plays a significant predictive role in the prognosis of rectal cancer patients." (PMID 40881169, 2025). "Additionally, our diagnostic and prognostic models, constructed using machine learning, highlight the significant predictive value of ASCC3 in combination with various immune-related genes, including JAK1, NFKB1, SEMA5A, NR2C2, CNTF and CREB1, for rectal cancer prognosis." (PMID 40881169, 2025).
respiratory failure (1 paper, 2024). The significant impairment of gas exchange within the lungs resulting in hypoxia, hypercarbia, or both, to the extent that organ tissue perfusion is severely compromised. "By inhibiting the JAK1 and JAK2 pathways, it can block the immune cascade and reduce viral replication, which is beneficial for reducing respiratory failure and mechanical ventilation." (PMID 38378889, 2024).
retinoblastoma (1 paper, 2025). A malignant tumor that originates in the nuclear layer of the retina. "Similarly, in retinoblastoma cells, curcumin downregulates JAK1 and STAT1/STAT3 phosphorylation while modulating miR-99a, which mechanistically leads to apoptotic cell death." (PMID 41020838, 2025). "By regulating miR-99a expression and reducing the phosphorylation of JAK1, STAT1, and STAT3, curcumin drives apoptotic cell death in retinoblastoma cells." (PMID 41020838, 2025).
SARS-CoV infection (1 paper, 2012). "STAT1 and JAK1 were indeed significantly upregulated in ferret lungs only during acute SARS-CoV infection." (PMID 23029269, 2012). "STAT1 and JAK1, key upstream mediators of integrated IRG gene expression upon phosphorylation, were significantly upregulated in ferret lungs only during acute SARS-CoV infection." (PMID 23029269, 2012).
Schamberg disease (1 paper, 2025). "These patients had the most common form of PPD, Schamberg disease, for a 1-6 month duration prior to starting JAK1 inhibitor therapy." (PMID 40034551, 2025).
sensitization (1 paper, 2014). "SNPs in or near JAK2, CNOT6, MAML1, CD40, IL-4R, and IL-5RA genes were associated with allergic sensitization and SNPs in or near JAK1, JAK3, IL5RA, FCER1A, and ADAM33 genes were associated with cockroach sensitization." (PMID 25505553, 2014). "In addition, SNPs in or near IL-4R, JAK1, and IL12B showed modest association with allergic sensitization." (PMID 25505553, 2014).
serous ovarian cancer (1 paper, 2025). "SK-OV-3, a serous ovarian cancer cell line, has been used to study the effects of Ruxolitinib, a JAK1/2 inhibitor, in combination with chemotherapeutic agents." (PMID 40662801, 2025).
serous retinal detachment (1 paper, 2026). "A case report of baricitinib, a selective JAK1 and JAK2 inhibitor, use in a patient with ocular and systemic features of seronegative RA showed resolution of anterior chamber cell, corneal infiltrates, vitreous opacity, and serous retinal detachment at 3 month follow-up." (PMID 41198980, 2026).
severe combined immunodeficiency (1 paper, 2018). Severe combined immunodeficiency (SCID) comprises a group of rare monogenic primary immunodeficiency disorders characterized by a lack of functional peripheral T lymphocytes resulting in early-onset severe respiratory infections and failure to thrive. "For example, mutant Jak1 and Jak3 mice have severe combined immunodeficiency (SCID), and Jak1 mutants also have neurological defects and poor survival past birth; knock out mutations in Jak2 are embryonic lethal, and mutations in the Jak family member Tyk2 result in poor response to pathogens." (PMID 30558204, 2018).
Sézary syndrome (1 paper, 2025). "This case demonstrated that both low- and high-dose oclacitinib may offer temporary clinical benefits in dogs with Sézary syndrome, potentially via JAK1 inhibition." (PMID 41473101, 2025).
T-cell neoplasms (1 paper, 2019). "Indeed, the T-cell neoplasms induced by transgenic STAT5B N642H was markedly suppressed by JAK1/2 inhibition." (PMID 30573779, 2019).
thyroid (1 paper, 2024). "Upon confirming the overactivation of the JAK1/2-STAT3 signaling pathway within the ATC cell lines and clinical samples, we proceeded to evaluate the effects of Ruxo using various thyroid cell lines, NTHY, TPC-1, BCPAP, IHH4, 8505 C, KHM-5M, C643, CAL-62 and BHT101 in vitro." (PMID 38336839, 2024).
toxic epidermal necrolysis (1 paper, 2025). Toxic epidermal necrolysis (TEN) is an acute and severe skin disease with clinical and histological features characterized by the destruction and detachment of the skin epithelium and mucous membranes. "The results showed a substantial association between apalutamide and Stephen Johnson Syndrome/toxic epidermal necrolysis, and the mechanism behind this association may be the binding of apalutamide to JAK1 and JAK2." (PMID 40017595, 2025).
trisomy 21 (1 paper, 2016). A chromosomal disorder consisting of the presence of an extra chromosome 21. "An shRNA screen determined that the interferon-activated kinases JAK1 and TYK2 suppress proliferation of trisomy 21 fibroblasts, and this defect is rescued by pharmacological JAK inhibition." (PMID 27472900, 2016).
ulcer (1 paper, 2019). "The GSE103412 dataset showed increased JAK1/2 in ulcer patients after radiation therapy." (PMID 32117790, 2019).
urothelial carcinoma (1 paper, 2019). A malignant neoplasm derived from the transitional epithelium of the urinary tract (urinary bladder, ureter, urethra, or renal pelvis). "Our data suggest loss of function JAK1 mutations are a risk factor for lower tumor cell PD-L1 expression which could impair responsiveness to anti-PD-1 therapy used for advanced urothelial carcinoma." (PMID 31552026, 2019). "Our results have implications for patients with rare JAK1 PID and, more broadly, inform development of biomarker and targeted therapies for urothelial carcinoma." (PMID 31552026, 2019).
vasculitis (1 paper, 2024). "Another study (SELECT-GCA) is underway to determine the role of upadacitinib, a selective JAK1 inhibitor, in the treatment of this vasculitis (ClinicalTrials ID: NCT03725202)." (PMID 38334659, 2024).